SIRPB1 (signal regulatory protein beta 1)
Description:
Immunoglobulin-like cell surface receptor involved in the negative regulation of receptor tyrosine kinase-coupled signaling processes. Immunoglobulin-like cell surface receptor involved in the negative regulation of receptor tyrosine kinase-coupled signaling processes. Also participates in the recruitment of tyrosine kinase SYK. Triggers activation of myeloid cells when associated with TYROBP.
Synonyms: SIRP-beta-1; CD172b; SIRB1
Tractability: Antibody: UniProt places it where antibodies can reach, with high confidence; its Gene Ontology location is reachable by antibodies, with high confidence; UniProt predicts a signal peptide or a membrane-spanning region. PROTAC: ubiquitination databases record sites on it; its protein half-life has been measured.
Gene: Protein-coding gene on chromosome 20 (1,561,385 to 1,620,061, reverse strand). Ensembl gene ENSG00000101307.
Subcellular location: Membrane; Cell membrane
Subcellular location (Human Protein Atlas): Vesicles; Centrosome
Pathways (Reactome):
Immune System: DAP12 interactions; Neutrophil degranulation
Cell-Cell communication: Signal regulatory protein family interactions
Gene Ontology:
Molecular function: protein binding
Biological process: cell surface receptor signaling pathway; positive regulation of phagocytosis; positive regulation of T cell activation; signal transduction
Cellular component: plasma membrane; cell surface; secretory granule membrane; membrane
Genetic constraint (gnomAD): Loss-of-function variants: 26 observed, 30.34 expected, observed/expected ratio (o/e) 0.86, 90% interval 0.63 to 1.19. The upper end of that interval is the gene's LOEUF score, 1.19, which puts it in group 5 of 6, group 1 being the genes least tolerant of losing a copy. Missense variants: 481 observed, 491.89 expected, observed/expected ratio (o/e) 0.98, 90% interval 0.91 to 1.05. Synonymous variants: 203 observed, 198.73 expected, observed/expected ratio (o/e) 1.02, 90% interval 0.91 to 1.15.
Homologues: Orthologues: dog SIRPA (65% identical), mouse Sirpa (54% identical), mouse Sirpb1b (53% identical), mouse Sirpb1c (52% identical), mouse Sirpb1a (52% identical), rat Sirpa (52% identical), macaque SIRPA (32% identical), mouse Gm5150 (26% identical), rat LOC100909964 (24% identical), mouse Sirpd (19% identical), rat AABR07008876.1 (19% identical). Paralogues in human: SIRPA (78% identical), SIRPG (74% identical), SIRPD (19% identical), SIRPB2 (18% identical).
Diseases named in the same sentence as SIRPB1 in open-access papers:
SIRPB1 is named in the same sentence as 27 diseases in open-access papers, as found by Europe PMC text mining. Sharing a sentence is not in itself a finding about the gene and the disease. The quoted sentences say what the papers report.
Crohn disease (3 papers, 2023 to 2024). A gastrointestinal disorder characterized by chronic inflammation involving all layers of the intestinal wall, noncaseating granulomas affecting the intestinal wall and regional lymph nodes, and transmural fibrosis. "SIRPB1 is a potential oncogene capable of activating Akt signaling to stimulate prostate cancer proliferation, and the SIRPB1 gene confers susceptibility to Crohn’s disease." (PMID 38283146, 2023).
Alzheimer disease (2 papers, 2011 to 2019). A progressive, neurodegenerative disease characterized by loss of function and death of nerve cells in several areas of the brain leading to loss of cognitive function such as memory and language. "TYROBP/DAP12 forms complexes with ectodomains of immune receptors (TREM2, SIRPβ1, CR3) associated with Alzheimer’s disease (AD) and is a network hub and driver in the complement subnetwork identified by multi-scale gene network studies of postmortem human AD brain." (PMID 30283031, 2019).
schizophrenia (2 papers, 2013 to 2017). A major psychotic disorder characterized by abnormalities in the perception or expression of reality. "In summary, the SIRPB1 mediated LCK and SYK gene activation are associated with schizophrenia related to BA22 tissue specific gene." (PMID 24564241, 2013). "Using a schizophrenia-hepatocellular carcinoma network, the authors found that some schizophrenia candidate genes (SIRPB1, SYK, and LCK) and genes mediating the immune responses in the etiology mechanism of schizophrenia (IL-2 and TREM-1/DAP12) may also function as tumor-suppressor genes." (PMID 29254248, 2017). "SYK and LCK were the over-expression genes with high betweenness, however, SIRPB1 was an over-expressed gene for schizophrenia and directly linked to SYK from the QQPPI of SHCN, and it may have an implication of a potential disease mechanism for schizophrenia." (PMID 24564241, 2013). "The results help to explain that the over-expression genes SIRPB1, LCK and SYK are responsible for one of the possible disease mechanisms for schizophrenia." (PMID 24564241, 2013). "For example, the over-expressing schizophrenia candidate genes, SIRPB1, SYK and LCK, are responsible for signal transduction in cytokine production; immune responses involving IL-2 and TREM-1/DAP12 pathways are relevant for the etiology mechanism of schizophrenia." (PMID 24564241, 2013). "Another responsible pathway involves the IL-2 pathway which Interleukin-2 binds to the IL-2 receptor to activate LCK and SYK, which helps explain that the over-expression genes: SIRPB1, LCK and SYK might be responsible for one of the possible disease mechanisms for schizophrenia." (PMID 24564241, 2013).
astrocytoma (1 paper, 2024). "We used the Single Cell Portal to evaluate datasets for glioblastoma and astrocytoma in order to identify the cells in gliomas that had high expression of SIRPB1." (PMID 38594692, 2024).
autoimmune disease (1 paper, 2022). A disorder resulting from loss of function or tissue destruction of an organ or multiple organs, arising from humoral or cellular immune responses of the individual to their own tissue constituents. "Based on all above, SIRPB1 showed strong association with autoimmune diseases, which may be involved in the mechanisms of JIA and provide opportunities to develop new drugs that act on these targets." (PMID 35967305, 2022).
Burkitt lymphoma (1 paper, 2021). A rare form of malignant mature B-cell non-Hodgkin lymphoma. "This individual had a de novo, homozygous structural variant in SIRPB1, the 2nd overall ranked gene for Burkitt’s lymphoma; no other child in the family shared this variant." (PMID 34624066, 2021). "For Family 3 (Burkitt’s lymphoma), TNNT3, SIRPB1, TRMT1, ITGB4, and DCHS1 were the top-five ranked genes." (PMID 34624066, 2021).
glioma (1 paper, 2024). A benign or malignant brain and spinal cord tumor that arises from glial cells (astrocytes, oligodendrocytes, ependymal cells). "Our study, for the first time, investigate SIRPB1’s role in glioma’s immune microenvironment, and associates high SIRPB1 levels with poor prognosis and key clinical markers, such as WHO grade, IDH status, and 1p/19q co-deletion." (PMID 38594692, 2024). "Through the follow-up of 70 patients with different grades of gliomas in this study center, we found that the expression of SIRPB1 was associated with poor prognosis." (PMID 38594692, 2024). "Combined with the existing results and literature, we can preliminarily explain the role of SIRPB1 in glioma-associated macrophages." (PMID 38594692, 2024). "Consistent with the notion that glioma-associated macrophages exhibit both M1 and M2 features, further cell line analyses and immunofluorescence staining verified SIRPB1 expression in monocytes and macrophages." (PMID 38594692, 2024). "The high expression of SIRPB1 is associated with poor prognosis in glioma and kidney renal clear cell carcinoma, but it seems to be a protective factor in skin cutaneous melanoma." (PMID 38594692, 2024). "To further elucidate SIRPB1's role in glioma, we created a PPI network with 246 nodes and 931 edges using Metascape." (PMID 38594692, 2024). "This study, we analyzed 1152 normal samples from the GTEx database and 670 glioma samples from the TCGA database to investigate the relationship between the expression of SIRPB1 and clinicopathological features." (PMID 38594692, 2024). "Significantly higher levels of SIRPB1 expression were found in gliomas, which had an adverse effect on the immune milieu and correlated poorly with patient survival." (PMID 38594692, 2024). "Considering the predominant expression of the SIRP family in neurons and myeloid cells and the high frequency of TAMs in gliomas, Our attention was drawn to SIRPB1's function in TAMs." (PMID 38594692, 2024). "In the areas where glioma cells gathered, SIRPB1 staining increased with the increase of glioma grade." (PMID 38594692, 2024). "Although SIRPB1’s functions were initially identified outside of oncological settings, new research highlights the critical role it plays in the glioma immunological landscape, especially when it comes to spleen tyrosine kinase (SYK)." (PMID 38594692, 2024). "Subsequent cultures of glioma cell lines, macrophages, monocytes, and microglial cells in both humans and mice confirmed that SIRPB1 is primarily expressed in macrophages and monocytes." (PMID 38594692, 2024). "Logistic regression analysis further confirmed SIRPB1's significant association with WHO grade, IDH status, 1p/19q co-deletion, primary therapy outcome, and EGFR status in glioma samples." (PMID 38594692, 2024). "In the fresh glioma tissue samples we collected, the expression of SIRPB1 detected by Western blot was significantly higher than that in paracancerous tissues." (PMID 38594692, 2024). "We used the CCLE database to analyze SIRPB1 expression in monocyte and common glioma cell lines in order to validate our hypothesis." (PMID 38594692, 2024). "THP-1 monocytes showed significantly higher SIRPB1 levels than glioma cell lines." (PMID 38594692, 2024). "Polychromatic immunofluorescence revealed that SIRPB1 co-localizes with TMEM119 (microglia marker), CD86 (M1 macrophage marker), and CD163 (M2 macrophage marker) indicating that SIRPB1 is predominantly found in TAMs, which in glioma tissues exhibit both M1 and M2 characteristics." (PMID 38594692, 2024). "This work established SIRPB1’s function in the glioma inhibitory immune milieu." (PMID 38594692, 2024). "SIRPB1 expression is upregulated in various tumor types, including gliomas, and is known to contribute to tumor progression; nevertheless, its function in the immune milieu of gliomas is still mainly unknown." (PMID 38594692, 2024). "According to our findings, SIRPB1 might be a useful prognostic indicator for gliomas." (PMID 38594692, 2024).
glioma (continued). "Our knowledge of the significance of SIRPB1 and SYK signaling in cancer biology has significantly changed as a result of this interaction's recognition as being important in glioma immune response modulation." (PMID 38594692, 2024). "Our study demonstrates that glioma cells can be activated by macrophages via SIRPB1, subsequently reprogramming the TME, suggesting that SIRPB1 could serve as a promising therapeutic target for gliomas." (PMID 38594692, 2024). "Moreover, SIRPB1 gene knockout THP-1 cell lines were constructed using CRISPR/Cas9 and were induced into a co-culture of macrophages and glioma cells in vitro to learn more about the role of SIRPB1 in the glioma immune milieu." (PMID 38594692, 2024). "It is also established that SIRPB1 may not “exist” but rather be “involved” in the pathological process of glioma in conjunction with the outcomes of in vitro investigations." (PMID 38594692, 2024). "We have shown a negative correlation between high levels of SIRPB1 and important clinical markers such as WHO grade, IDH status, and 1p/19q co-deletion, which is the first study to investigate SIRPB1's function in the immune milieu of gliomas." (PMID 38594692, 2024).
immunodeficiencies (1 paper, 2021). "SIRPB1 is involved in cell signaling as a transmembrane glycoprotein receptor and may be associated with immunodeficiencies." (PMID 34624066, 2021).
oral cancer (1 paper, 2013). "In view of this, the occurrence of this particular gene with oral cancers reflects the need for further studies on SIRPB1 genes to understand their role in oral cancer progression." (PMID 23405089, 2013).
primary myelofibrosis (1 paper, 2022). Myelofibrosis with myeloid metaplasia is a myeloproliferative disease with annual incidence of approximately 1 case per 100,000 individuals and age at diagnosis around 60 (an increased prevalence is noted in Ashkenazi Jews). "While not much is known about SIRPD, the amplification of SIRPB1 has been associated with primary myelofibrosis, a disease of the bone marrow." (PMID 35887382, 2022).
viral infection (1 paper, 2025). "The median expression of some genes (CTBP1, LAPTM4B, CFAP45, DSC2, LAMP1, EXOG, RPS21, and SIRPB1) was higher in bacterial compared to viral infection." (PMID 41496780, 2025).
tumor (9 papers, 2013 to 2025). "Immunohistochemical staining of sections from patients with PMMC revealed statistically significant increases in expression of SIRPB1, AHNAK2, and XKR6 in tumor-associated regions compared with adjacent tissue." (PMID 41479783, 2025). "Monotherapy targeting SIRPB1 was reported to promote the cytotoxic and phagocytic activity of macrophages against tumor cells." (PMID 41033464, 2025). "SIRPB1 was predominantly found in macrophages or microglia, with low expression in tumor cells consistent with our Western blot and immunohistochemical findings." (PMID 38594692, 2024). "It was found that ligation of MY-1 to SIRPβ1 promoted TNFα secretion by macrophages and suppressed tumor growth through activation of a DAP12-Syk- MAPK signaling pathway." (PMID 35865547, 2022). "SIRPB1 is a member of the signal-regulatory protein (SIRP) family and the activation of this gene is involved in activating the SYK-JAK-STAT signalling, that regulates the proliferation and survival of cancer cells in tumor progression." (PMID 23405089, 2013). "Moreover, the antibody also binds the extracellular region of mouse SIRPβ1 and promoted anti-tumor immunity independent of macrophage-mediated ADCP." (PMID 35865547, 2022).
cancer (5 papers, 2013 to 2024). A tumor composed of atypical neoplastic, often pleomorphic cells that invade other tissues. "We compared the expression of SIRPB1 in normal GTEx samples with 33 TCGA cancer types using the Wilcoxon test." (PMID 38594692, 2024). "Elevated SIRPB1 levels were observed in several cancers, including GBM and LGG, while decreased levels were found in cancers like LUAD and PRAD (all P < 0.001)." (PMID 38594692, 2024). "In the second family in which MPT21 and two relatives were tested, we found four LP variants (BPIF1, BCORL1, ROPN1, and PRSS3) and four other cancer-related genes (TUBB2B, CFAP54, PSG2, and SIRPB1)." (PMID 39408606, 2024). "Variants in four genes (ROPN1, PRSS3, BPIFB1, and BCORL1) were detected in all individuals from Family 2, while four (TUBB2B, CAFAP54, PSG2, and SIRPB1) were exclusive of the MPT21 index case and her relative with cancer (MPT21.2)." (PMID 39408606, 2024).
adenocarcinoma (1 paper, 2015). A common cancer characterized by the presence of malignant glandular cells. "For adenocarcinoma specifically, DM was observed in promoters [hypermethylated RASL12; SPTAN1, mir-26a, hypomethylated NQO1, SIRPB1, NF1A] and gene bodies [hypermethylated AKAP13, ANK family, PRKCE, ROS1; hypomethylated FAM171A1, PARK2, BCAS3, RHOJ] and many others." (PMID 26683690, 2015).
genetic disorders (1 paper, 2025). "Among the prioritized custom CMA genes in the smallest custom CMA NDDi, KIAA1586, ASCL3, BTNL3, SIRPB1, and GLT1D1 exhibit high average shortest path length and low proximity, indicating vulnerability to genetic disorders." (PMID 40869915, 2025).
infection (1 paper, 2019). The state of being infected such as from the introduction of a foreign agent such as serum, vaccine, antigenic substance or organism. "Since SIRPB1 promotes neutrophil migration to the site of infection, the CNV deletion containing this gene is a protective factor." (PMID 31349540, 2019).
SIRPB1 also shares sentences with these, for which no sentence is quoted: prostate carcinoma (2 papers); bone metabolic disorders (1); breast carcinoma (1); cardiomyopathy (1); colorectal carcinoma (1); glioblastoma (1); hepatocellular carcinoma (1); melanoma (1); retinoblastoma (1); SAPHO syndrome (1); skin cutaneous melanoma (1).